PLA2G2F (phospholipase A2 group IIF)
Description:
Secretory calcium-dependent phospholipase A2 that primarily targets extracellular phospholipids. Hydrolyzes the ester bond of the fatty acyl group attached at the sn-2 position of phospholipids (phospholipase A2 activity), the catalytic efficiency decreasing in the following order: phosphatidylglycerols > phosphatidylethanolamines > phosphatidylcholines > phosphatidylserines. May play a role in lipid mediator production in inflammatory conditions, by providing arachidonic acid to downstream cyclooxygenases and lipoxygenases (By similarity).
Synonyms: sPLA2-IIF; GIIFsPLA2
Tractability: Small molecule: a high-quality ligand is known; it belongs to a druggable protein family. Antibody: its Gene Ontology location is reachable by antibodies, with high confidence; UniProt places it where antibodies can reach, with medium confidence; UniProt predicts a signal peptide or a membrane-spanning region. PROTAC: a small molecule that binds it is known.
Target class: Enzyme; Hydrolase
Gene: Protein-coding gene on chromosome 1 (20,139,323 to 20,150,381, forward strand). Ensembl gene ENSG00000158786.
Subcellular location: Secreted (Isoform 1); Cell membrane
Pathways (Reactome):
Metabolism: Acyl chain remodelling of PC; Acyl chain remodelling of PE; Acyl chain remodelling of PG; Acyl chain remodelling of PI; Acyl chain remodelling of PS; Synthesis of PA
Gene Ontology:
Molecular function: phospholipase A2 activity; calcium ion binding; phospholipid binding
Biological process: phosphatidylcholine acyl-chain remodeling; phosphatidylethanolamine acyl-chain remodeling; phosphatidylglycerol acyl-chain remodeling; phosphatidylserine acyl-chain remodeling; negative regulation of T cell proliferation; phosphatidylcholine metabolic process; phosphatidylglycerol metabolic process; arachidonate metabolic process; arachidonate secretion; lipid catabolic process; phospholipid metabolic process
Cellular component: cytosol; extracellular region; plasma membrane
Genetic constraint (gnomAD): Loss-of-function variants: 12 observed, 13.05 expected, observed/expected ratio (o/e) 0.92, 90% interval 0.59 to 1.48. The upper end of that interval is the gene's LOEUF score, 1.48, which puts it in group 6 of 6, group 1 being the genes least tolerant of losing a copy. Missense variants: 295 observed, 272.09 expected, observed/expected ratio (o/e) 1.08, 90% interval 0.99 to 1.19. Synonymous variants: 119 observed, 105.57 expected, observed/expected ratio (o/e) 1.13, 90% interval 0.97 to 1.31.
Homologues: Orthologues: chimpanzee PLA2G2F (96% identical), macaque PLA2G2F (77% identical), dog PLA2G2F (75% identical), rabbit PLA2G2F (75% identical), pig PLA2G2F (74% identical), guinea pig PLA2G2F (73% identical), rat Pla2g2f (73% identical), mouse Pla2g2f (72% identical), Caenorhabditis elegans C03H5.4 (20% identical), Caenorhabditis elegans C07E3.9 (20% identical). Paralogues in human: PLA2G2D (30% identical), PLA2G2A (27% identical), PLA2G2E (27% identical), PLA2G5 (26% identical), OC90 (25% identical), PLA2G10 (23% identical), PLA2G2C (22% identical), PLA2G1B (21% identical).
Diseases named in the same sentence as PLA2G2F in open-access papers:
PLA2G2F is named in the same sentence as 15 diseases in open-access papers, as found by Europe PMC text mining. Sharing a sentence is not in itself a finding about the gene and the disease. The quoted sentences say what the papers report.
psoriasis (6 papers, 2017 to 2025). An autoimmune condition characterized by red, well-delineated plaques with silvery scales that are usually on the extensor surfaces and scalp. "sPLA2-IIF (encoded by Pla2g2f) is exclusively expressed in epidermal keratinocytes and upregulated in psoriasis and skin cancer." (PMID 40391916, 2025). "Consistent with this, Pla2g2f deficiency in keratinocytes markedly impairs the induction of several psoriasis markers in response to IL-17A or IL-22." (PMID 30546811, 2018). "By driving a unique lipid pathway, PLA2G2F promotes the development of psoriasis, contact dermatitis and skin cancer." (PMID 36700214, 2022). "Of these, PLA2G2F is the best studied in skin homeostasis, where it has been proven to be important in hyperproliferative epithelial diseases such as psoriasis and skin cancer." (PMID 36700214, 2022). "This led to our identification of 3 members of the PLA2 family, both soluble (PLA2G2F) and cytoplasmic (PLA2G4D and PLA2G4E), as a critical pathogenic pathway shared between PRP and psoriasis." (PMID 34491907, 2021). "Moreover, overexpression of PLA2G2F (one of the sPLA2s) in a transgenic mouse model led to development of chronic epidermal hyperplasia and hyperkeratosis, similar to the pathology of psoriasis." (PMID 34491907, 2021). "Among the overlapping PRP and psoriasis DEGs were several psoriasis hallmark genes, including proinflammatory cytokines and chemokines, skin barrier–related genes, and several PLA2 family genes (PLA2G2F, PLA2G4D, and PLA2G4E)." (PMID 34491907, 2021). "Here, we show that PLA2G2F (sPLA2) and PLA2G4D/PLA2G4E (cPLA2s) are highly expressed in the epidermis of both PRP and psoriasis." (PMID 34491907, 2021). "The major common pathway shared between psoriasis and PRP involves the phospholipases PLA2G2F, PLA2G4D, and PLA2G4E, which were found to be primarily expressed in the epidermis." (PMID 34491907, 2021). "In addition, we further confirmed that PLA2 was commonly elevated in psoriasis, although the expression levels of PLA2G4B and PLA2G2F were incompatible with some previous studies, possibly due to sample size and individual variability." (PMID 36700214, 2022). "Indeed, the skin levels of P-LPE are correlated well with those of sPLA2-IIF expression in several skin disease models, and topical application of P-LPE to Pla2g2f−/− skin in vivo or supplementation of Pla2g2f−/− keratinocytes with P-LPE ex vivo restores the psoriasis-related phenotypes." (PMID 30546811, 2018).
atherosclerosis (2 papers, 2015 to 2018). A disease characterized by the build-up of fatty material and calcium deposition in the arterial wall resulting in partial or complete occlusion of the arterial lumen. "The common mechanisms shared in both are linked with atherosclerosis signaling and inflammatory response with at least the following target genes: Tnfrsf12a, Pla2g2f, Il1f9, Col1a1, Col1a2, and Col3a1 in brain, while Tnfrsf12a, SELP, SELE, IL6, and IL1A in myocardium." (PMID 29681850, 2018). "PLA2G2F has a twofold preference for AA over linoleic acid in vitro and that its expression generally increases in the aorta consecutively with advance of atherosclerosis." (PMID 25889305, 2015). "Ten key regulated genes (including Pla2g2f, Il1f9, Col1a1, Col1a2, and Col3a1 in the brain, while SELP, SELE, IL6, and IL1A in the myocardium, and Tnfrsf12a in both) are correlative with atherosclerosis signaling and inflammatory response." (PMID 29681850, 2018).
bladder cancer (1 paper, 2023). "Effect of IP6K2 and PLA2G2F on cell proliferation in vitro was explored to determine their role in bladder cancer cell proliferation." (PMID 38017469, 2023). "IP6K2 and PLA2G2F expression in bladder cancer and adjacent tissues was detected using RT-qPCR." (PMID 38017469, 2023). "In addition, PLA2G2F knockdown also promotes proliferation and colony formation of bladder cancer cells." (PMID 38017469, 2023).
colorectal cancer (1 paper, 2008). A primary or metastatic malignant neoplasm that affects the colon or rectum. "Interestingly, the PLA2G2A, PLA2G2C, PLA2G2D, PLA2G2E, PLA2G2F and PLA2G5 genes reside within the same region of human chromosome 1 at p35–36.1, a region frequently altered in colorectal cancer." (PMID 18212756, 2008).
inflammatory skin disorders (1 paper, 2021). "We further confirmed expression of PLA2G2F and PLA2G4D in other hyperproliferative and inflammatory skin disorders, including squamous cell carcinoma, suggesting that expression of these PLA2s is a common pathway in diseases characterized by epithelial proliferation." (PMID 34491907, 2021).
periodontitis (1 paper, 2024). An acute or chronic inflammatory process that affects the tissues that surround and support the teeth. "Other possibly relevant downregulated genes to the pathogenesis of T2DM-related periodontitis are keratin 76, critical for epidermal integrity, and the PLA2G2F, as PLA2s are involved in host defense and barrier function." (PMID 38241313, 2024).
tumor (2 papers, 2008 to 2022). "AP2S1, P3H4 (SC65), SPAG4, PLA2G2F, PTPN6, RAC3, and ETV7 were identified as candidate tumor-associated antigens." (PMID 35814377, 2022). "No variation in expression between the tumours and normal mucosa was observed for PLA2G1B, PLA2G2A, PLA2G2F, PLA2G10, PLA2G12A and PLA2G12B and for the M-type sPLA2 receptor (PLA2R1)." (PMID 18212756, 2008).
cancer (1 paper, 2023). A tumor composed of atypical neoplastic, often pleomorphic cells that invade other tissues. "Expression levels of IP6K2 and PLA2G2F were significantly downregulated in cancer tissues compared with their expression levels in adjacent tissues." (PMID 38017469, 2023).
PLA2G2F also shares sentences with these, for which no sentence is quoted: skin cancer (4 papers); diabetes (1); diabetic retinopathy (1); melanoma (1); renal disease (1); skin disorder (1); squamous cell carcinoma (1).